FCHSD1 (FCH and double SH3 domains 1)
Description:
Promotes actin polymerization mediated by SNX9 and WASL.
Synonyms: NWK2; FLJ00007
Tractability: PROTAC: ubiquitination databases record sites on it; its protein half-life has been measured.
Gene: Protein-coding gene on chromosome 5 (141,639,302 to 141,651,430, reverse strand). Ensembl gene ENSG00000197948.
Subcellular location: Cytoplasm; Perikaryon; Cell projection; Cytoplasmic vesicle
Subcellular location (Human Protein Atlas): Nucleoplasm; Cytosol
Gene Ontology:
Biological process: neuromuscular synaptic transmission; positive regulation of actin filament polymerization; regulation of actin filament polymerization; membrane organization; positive regulation of cytoskeleton organization; positive regulation of supramolecular fiber organization
Cellular component: cuticular plate; cytoplasm; cytoplasmic vesicle; neuromuscular junction; perikaryon; recycling endosome; cytosol
Genetic constraint (gnomAD): Loss-of-function variants: 109 observed, 96.91 expected, observed/expected ratio (o/e) 1.12, 90% interval 0.96 to 1.32. The upper end of that interval is the gene's LOEUF score, 1.32, which puts it in group 5 of 6, group 1 being the genes least tolerant of losing a copy. Missense variants: 820 observed, 861.53 expected, observed/expected ratio (o/e) 0.95, 90% interval 0.9 to 1.01. Synonymous variants: 291 observed, 339.69 expected, observed/expected ratio (o/e) 0.86, 90% interval 0.78 to 0.94.
Homologues: Orthologues: chimpanzee FCHSD1 (99% identical), macaque FCHSD1 (96% identical), rabbit FCHSD1 (92% identical), pig FCHSD1 (91% identical), dog FCHSD1 (91% identical), guinea pig FCHSD1 (91% identical), mouse Fchsd1 (91% identical), rat Fchsd1 (91% identical), tropical clawed frog fchsd1 (49% identical), Drosophila melanogaster nwk (28% identical), Caenorhabditis elegans C26C6.8 (9% identical). Paralogues in human: FCHSD2 (40% identical).
Diseases named in the same sentence as FCHSD1 in open-access papers:
FCHSD1 is named in the same sentence as 25 diseases in open-access papers, as found by Europe PMC text mining. Sharing a sentence is not in itself a finding about the gene and the disease. The quoted sentences say what the papers report.
cholangiocarcinoma (1 paper, 2025). A carcinoma that arises from the intrahepatic biliary tree (intrahepatic cholangiocarcinoma) or from the junction, or adjacent to the junction, of the right and left hepatic ducts (hilar cholangiocarcinoma). "In cholangiocarcinoma, the genetic alterations of FCHSD1 are “amplification” (2.78%)." (PMID 40535123, 2025).
colorectal cancer (1 paper, 2025). A primary or metastatic malignant neoplasm that affects the colon or rectum. "In colorectal cancer, the genetic variation of FCHSD1 was “mutation” (4.35% and 2.53%)." (PMID 40535123, 2025).
glioblastoma (1 paper, 2025). The most malignant astrocytic tumor (WHO grade IV). "In contrast, FCHSD1 expression significant enhancement was found in KIRC, glioblastoma multiforme (GBM), PAAD." (PMID 40535123, 2025).
lung adenocarcinoma (1 paper, 2025). A carcinoma that arises from the lung and is characterized by the presence of malignant glandular epithelial cells. "For lung adenocarcinoma (LUAD) and thyroid carcinoma (THCA), the correlation between the expression of FCHSD1 and staging was not obvious." (PMID 40535123, 2025).
oligodendroglioma (1 paper, 2025). A well-differentiated (WHO grade II), diffusely infiltrating neuroglial tumor, typically located in the cerebral hemispheres. "In addition, according to the cBioPortal database, missense mutations in FCHSD1 were found to be the main type of genetic alterations, and G559R alterations were detected in 2 cases of UCEC and 1 case of oligodendroglioma." (PMID 40535123, 2025).
ovarian serous cystadenocarcinoma (1 paper, 2025). A malignant serous cystic epithelial neoplasm arising from the ovary. "FCHSD1 protein expression is reduced in uterine corpus endometrial carcinoma (UCEC), ovarian serous cystadenocarcinoma (OV) and liver hepatocellular carcinoma (LIHC) compared to normal tissue." (PMID 40535123, 2025).
pancreatic adenocarcinoma (1 paper, 2025). "Through further comparison of TCGA + GTEx database, it was found that FCHSD1 was significantly elevated in five tumor types: CHOL, HNSC, KIRC, KIRP, and pancreatic adenocarcinoma (PAAD)." (PMID 40535123, 2025).
paraganglioma (1 paper, 2025). A benign or malignant neoplasm arising from paraganglia located along the sympathetic or parasympathetic nerves. "For cancers of different molecular subtypes, significant associations in FCHSD1 expression were shown in 11 cancer types, including LGG, pheochromocytoma and paraganglioma (PCPG), COAD, PRAD, BRCA, UCEC, stomach adenocarcinoma (STAD), LIHC, HNSC, OV, and GBM." (PMID 40535123, 2025).
renal carcinoma (1 paper, 2025). A carcinoma arising from the epithelium of the renal parenchyma or the renal pelvis. "The expression and function of FCHSD1 in renal cancer cells and tissues have also been biologically validated in vitro." (PMID 40535123, 2025). "To further explore the role of FCHSD1 in the malignant progression of renal cancer, we silenced its expression in cell lines." (PMID 40535123, 2025). "The results revealed that FCHSD1 was highly expressed in renal cancer tissues compared with adjacent tissues." (PMID 40535123, 2025). "In vitro experiments revealed that the expression of FCHSD1 in renal cancer cells and tissues was higher than that in normal cells and adjacent non-cancerous tissues." (PMID 40535123, 2025). "Firstly, the number of validations for FCHSD1 expression levels in tissues is relatively small, and we only validated FCHSD1 expression in renal cancer cells and tissues." (PMID 40535123, 2025). "Furthermore, to further verify the expression of FCHSD1 in renal cancer patients, we conducted qRT-PCR on renal cancer tissues and adjacent non-cancerous tissues from multiple patients." (PMID 40535123, 2025). "Overall, downregulation of FCHSD1 expression can inhibit the malignant progression of renal cancer." (PMID 40535123, 2025). "Furthermore, we validated the expression levels of FCHSD1 in normal renal tubular epithelial cells and five renal cancer cell lines, as well as in adjacent non-cancerous tissues and renal cancer tissues from patients with renal cancer through in vitro experiments." (PMID 40535123, 2025).
cancer (1 paper, 2025). A tumor composed of atypical neoplastic, often pleomorphic cells that invade other tissues. "Through analysis with the GEPIA platform and R package, we discovered that enhanced expression of FCHSD1 is associated with poor prognosis in several cancers." (PMID 40535123, 2025). "We utilized the cBioPortal website to investigate the genetic alterations of FCHSD1 in human cancers and found that the major genetic alterations of FCHSD1 in cancers are mutations, structural variations, amplifications, and deep deletions." (PMID 40535123, 2025). "This study aims to provide a thorough analysis of FCHSD1 in pan-cancer, in order to reveal its potential role and underlying mechanisms in the development and clinical outcomes of various cancers." (PMID 40535123, 2025). "High FCHSD1 expression levels were found to be associated with shorter RFS in cancers such as LGG (p=5.8e-07) and STAD (p=0.01)." (PMID 40535123, 2025). "In conclusion, the results of survival curve and ROC curve analysis showed that FCHSD1 is a valuable diagnostic biomarker for many types of cancer, mainly including LGG, KIRC, BLCA." (PMID 40535123, 2025). "To systematically elucidate the mutational characteristics and biological function of FCHSD1 in tumor progression, we used the cBioPortal website to study the genetic alteration status of FCHSD1 in human pan-carcinoma." (PMID 40535123, 2025). "FCHSD1 has high diagnostic accuracy (AUC greater than 0.7) for most cancers." (PMID 40535123, 2025). "LGG, LIHC, and PRAD are the cancer phenotypes most associated with FCHSD1 expression of all tumors." (PMID 40535123, 2025). "Our study systematically analyzed FCHSD1 in a pan-carcinogenic manner, evaluated the potential association of FCHSD1 expression with pathological stage, immunophenotype, immune cell infiltration, genetics, prognosis, drug sensitivity, etc. in various cancer types." (PMID 40535123, 2025). "Further comparison using the TCGA + GTEx database with R packages revealed that FCHSD1 increased in 5 types of cancer." (PMID 40535123, 2025). "We note that FCHSD1 differs in immunoisoforms and molecular subtypes of different cancers and is the lowest expressed in human cancers with C4 and C5 immune subtypes." (PMID 40535123, 2025). "Cox proportional hazards regression confirmed the prognostic significance of FCHSD1 across multiple cancers." (PMID 40535123, 2025). "In order to investigate the relationship between FCHSD1 expression levels and the prognosis of cancer patients, we conducted survival correlation analysis on pan-cancer using several databases." (PMID 40535123, 2025). "Higher expression of FCHSD1 predicts worse outcomes for several cancer types, such as CHOL and KIRC." (PMID 40535123, 2025). "In these cancers, FCHSD1 expression was positively correlated with Th1 and Th17 infiltration in CD4T cell subsets, while FCHSD1 expression was negatively correlated with Th2 infiltration." (PMID 40535123, 2025). "Future research should prioritize the development of FCHSD1-targeted molecular therapies to suppress tumor progression, invasion, and metastasis across multiple cancer types." (PMID 40535123, 2025). "We explored the role of FCHSD1 expression in human cancer immunity and molecular subtypes through the TISIDB website." (PMID 40535123, 2025). "These cancer patients were divided into high and low FCHSD1 expression groups based on the median expression of FCHSD1." (PMID 40535123, 2025). "Firstly, we utilized GEPIA to evaluate the impact of FCHSD1 expression levels on the prognosis of pan-cancer patients." (PMID 40535123, 2025). "The results showed that high FCHSD1 expression was associated with shorter overall survival (OS) in cancer patients such as KIRC (p=0.001) and LGG (p<0.001), while increased FCHSD1 expression in BLCA (p=0.002) patients indicated prolonged OS." (PMID 40535123, 2025). "High FCHSD1 expression was positively correlated with immune cell infiltration in different cancer types." (PMID 40535123, 2025).
cancer (continued). "FCHSD1 plays different roles in the occurrence and development of different cancers, such as COAD, KIRC, BLCA, and LIHC." (PMID 40535123, 2025). "In summary, our study indicates that FCHSD1 mRNA expression is significantly increased in various cancer tissues compared with normal tissues." (PMID 40535123, 2025). "In order to further elucidate the prognostic role of FCHSD1 in these cancers, a Cox proportional hazards regression model was established to evaluate the prognostic factors." (PMID 40535123, 2025). "At the same time, we found through the ROC curve of cancer that the expression of FCHSD1 also has a strong predictive value for the prognosis of these cancers." (PMID 40535123, 2025). "Subsequently, we utilized R packages to establish the correlation between FCHSD1 expression and the prognosis of cancer patients." (PMID 40535123, 2025). "The role of FCHSD1 expression in human cancer immunity and molecular subtypes is explored through the TISIDB website." (PMID 40535123, 2025). "To further explore FCHSD1 expression in human cancers obtained from different stages, we analyzed the relationship between FCHSD1 and tumor stages using GEPIA." (PMID 40535123, 2025). "We need to use different methods, such as immunohistochemistry, to verify FCHSD1 expression in various cancer tissues." (PMID 40535123, 2025). "We note that FCHSD1 is the lowest expressed in human cancers of C4 and C5 subtypes, and specifically in LGG, LIHC, LUSC, KIRC, KIRP, PRAD." (PMID 40535123, 2025). "We also evaluated the correlation between FCHSD1 expression and different cancer stage classifications." (PMID 40535123, 2025). "The genetic alteration status of FCHSD1 in human pan-cancer was studied using the cBioPortal website." (PMID 40535123, 2025). "At the same time, FCHSD1 affects immune cell infiltration in some cancers." (PMID 40535123, 2025). "Secondly, although FCHSD1 expression is correlated with immune responses and clinical survival in human malignancies, we are uncertain about how FCHSD1 affects the clinical survival of cancer patients through immune pathways." (PMID 40535123, 2025). "TIMER results showed that FCHSD1 expression increased in 13 types of cancer." (PMID 40535123, 2025). "FCHSD1 expression was significantly altered in 11 cancer types." (PMID 40535123, 2025). "In summary, targeting endocytosis mechanisms may be a viable and promising therapeutic strategy for cancer and metastasis, and FCHSD1 and related protein networks may be a viable entry point." (PMID 40535123, 2025). "FCHSD1 has the potential to serve as a prognostic and immunological marker for pan-cancer, and may also be a crucial target for future immunotherapy." (PMID 40535123, 2025). "The TIMER database was used to elucidate whether FCHSD1 affects immune infiltration in human cancer." (PMID 40535123, 2025). "Therefore, FCHSD1 may serve as a valuable biomarker for cancer diagnosis, prognosis prediction, and immune infiltration assessment in human malignancies." (PMID 40535123, 2025). "In addition, the expression of FCHSD1 also differs in different immune subtypes of one cancer type." (PMID 40535123, 2025). "Therefore, FCHSD1 may be a potential therapeutic target or biomarker for multiple types of cancer." (PMID 40535123, 2025). "We also investigated the correlation between FCHSD1 and the major histocompatibility complexes, immunosuppressants, immunostimulants, chemokines, and receptors expressed in the tumor microenvironment (TME) of these cancers." (PMID 40535123, 2025). "At present, there are no relevant pan-cancer comprehensive studies on the predictive potential and immune infiltration of FCHSD1 for cancer." (PMID 40535123, 2025). "However, there is no systematic analysis of FCHSD1 in pan-carcinoma." (PMID 40535123, 2025).
tumor (1 paper, 2025). "In COAD, kidney chromophobe (KICH), stage IV tumor tissue was associated with higher expression of FCHSD1 compared to other stages." (PMID 40535123, 2025). "In order to delve deeper into the molecular mechanisms of FCHSD1 in tumor development, we screened for FCHSD1 binding proteins to conduct protein-protein interaction (PPI) network analysis." (PMID 40535123, 2025). "Using data from the TCGA database, the expression of FCHSD1 in tumor tissue and normal controls was compared by TIMER." (PMID 40535123, 2025). "The results revealed a significant correlation between FCHSD1 expression and tumor purity in 13 types of tumors, with a predominant negative correlation." (PMID 40535123, 2025). "FCHSD1 expression was found to be elevated in tumor tissues compared to adjacent tissues." (PMID 40535123, 2025). "FCHSD1 may functionally cooperate with interacting genes (e.g., SBK1, ITSN2, and FNBP4) to collectively drive tumor malignancy, thus warranting further mechanistic investigations to elucidate these molecular interactions." (PMID 40535123, 2025). "FCHSD1 may functionally interact with SBK1, ITSN2, and FNBP4 to collectively regulate malignant tumor progression." (PMID 40535123, 2025).
FCHSD1 also shares sentences with these, for which no sentence is quoted: cervical squamous cell carcinoma (1 paper); chronic obstructive pulmonary disease (1); colon adenocarcinoma (1); endocervical adenocarcinoma (1); esophageal carcinoma (1); genitourinary cancer (1); head and neck squamous cell carcinoma (1); pheochromocytoma (1); prostate adenocarcinoma (1); renal clear cell carcinoma (1); renal papillary cell carcinoma (1); stomach adenocarcinoma (1); thyroid carcinoma (1); uterine corpus endometrial carcinoma (1).